TNF (tumor necrosis factor)
Diseases named in the same sentence as TNF in open-access papers (continued):
Sharing a sentence is not in itself a finding about the gene and the disease.
tumor (continued). "In mouse models of PDAC, supplementation with melatonin can specifically increase the number of CD11b+Ly6G+ neutrophils that with high TNFα activity within the tumor, killing tumor cells via direct cell-to-cell contact mechanisms and thereby inhibiting tumor growth." (PMID 38982491, 2024). "TNF-α is a pleiotropic cytokine produced mainly by tumor cells and macrophages." (PMID 38082190, 2024). "It is known that TAMs are accumulated in hypoxic areas of tumor tissue, and that they secrete various pro-angiogenic molecules including TNF-α, matrix metalloproteinase (MMP), and vascular endothelial growth factor (VEGF) to promote blood vessel formation in tumors." (PMID 39065562, 2024). "Hence, tumor necrosis factor-α (TNF-α) plays an essential role in regulating the inflammatory process in tumor development." (PMID 39518052, 2024). "Using TNF as positive control, we measured that neutrophil apoptosis was inhibited by the tumor cell supernatant while it was enhanced by A-1331852, as inferred from both Annexin V/7-AAD staining by flow cytometry and cleavage of caspase-3 by western blot (Fig. EV3C)." (PMID 38177532, 2024). "It has also reduced tumor volume and prevented tumorigenicity by reducing TNF-a levels." (PMID 39246660, 2024). "TNF-α has tumor cell-killing and immunomodulatory functions." (PMID 38371596, 2024). "TNF-α was associated with higher all-cause mortality among cases with HER2- tumours, but not in those with HER2+ tumours." (PMID 39342063, 2024). "To determine whether effector cytokines produced by these functional tissue PD1+CD39− CD8 T cells could promote tumor spheroid growth on their own, we tested recombinant human IFN-γ and TNF in tumor spheroid growth assays." (PMID 38226976, 2024). "Moreover, TAN-N1 indirectly regulates the recruitment and activation of CD8+ T cells by producing chemokines and pro-inflammatory cytokines such as CCL3, CCL9, CXCL10, TNF-α, and IL-12, thereby contributing to the restriction of tumor growth." (PMID 39450177, 2024). "Activated gd T cells secrete IFN-γ and TNF-α to inhibit tumor cell growth." (PMID 39748921, 2024). "In addition, proinflammatory cytokines such as IL‐8, MIF, TNF‐ α, and so on, were significantly upregulated in tumor tissues." (PMID 38041547, 2024). "Other algogenic substances, such as tumor-producing cytokines and tumor necrosis factors (TNF), also release nociceptive mediators because of the proteolytic activity induced by tissue damage, favoring nociceptor sensitization, which finally contributes to the sustenance of cancer-related pain." (PMID 38730655, 2024). "Interestingly, we also observed that OPN expression in tumor cells was also increased when they were treated with TNF-α or IL-1β, and a dual effect was shown when they were treated with both TNF-α and IL-1β." (PMID 39726047, 2024). "In addition, for SARIFA-positive cases, a significantly lower expression of TNFα was also observed in the tumor center (p = 0.011) compared to SARIFA-negative cases." (PMID 37874427, 2024). "Tumor-associated neutrophils (TANs) can inhibit T cell responses through expression of ARG1, PDL1, IL-10, and ROS, and TANs can actually induce CD8 T cell apoptosis through NO production and the TNFα pathway." (PMID 38254801, 2024). "In tumor cells, TNF-α triggers caspase-8, leading to GSDMC cleavage at the D365 amino acid." (PMID 38304430, 2024). "Meanwhile, the TME in colorectal cancer often shows a prominent inflammatory component with pro-inflammatory cytokines such as IL-6 and transforming growth factor alpha (TNF-α), which can promote tumor cell proliferation and survival through the activation of the STAT3 and NF-κB pathways." (PMID 39449800, 2024).
tumor (continued). "Eliminate pathogens and tumor cells through direct phagocytosis, activate T cells and NK cells through antigen presentation and secretion of proinflammatory cytokines and chemokines such as TNF-α, IL-1, and CXCL10." (PMID 38779867, 2024). "Klf5 deacetylation amplifies the FGF/TNF signaling interplay between iCAFs and tumor cells." (PMID 38781024, 2024). "While it has anticancer properties primarily through inducing cancer cell death—a process that can be harnessed for cancer therapy—it can also promote tumor growth in many cancer cells resistant to TNF-induced cytotoxicity by stimulating proliferation, survival, migration, and angiogenesis." (PMID 39253073, 2024). "Basophils not only enhance humoral immune function but also liberate intracellular agents causing anti-tumor immunity, including the chemokines CCL3 and CCL4, which expedite CD8+ T-cell infiltration, and the chemokines TNF-α and IL-6, which enhance inflammatory anti-tumor responses." (PMID 39816393, 2024). "Additionally, tumor cells and tumor-infiltrating lymphocytes produce cytokines and growth factors (e.g., TNF-α and IL6) in response to radiation and are mostly dose-dependent." (PMID 38136404, 2023). "Consequently, the STING pathway is activated, leading to the production of cytokines such as IFN-α and TNF, promoting tumor cell growth and chemoresistance." (PMID 37876939, 2023). "However, further examination, including ROC and multivariate analysis, indicated that the prognostic value of tumor TNF-α expression was limited." (PMID 37444550, 2023). "In a mouse model of breast cancer, the combination of IFN-γ and MPLA (Monophosphoryl Lipid A), a TLR4 ligand, results in the reduction of tumor growth and metastatic potential of cancer cells via reprogramming of TAMs into pro-inflammatory macrophages expressing TNFα and IL-12." (PMID 37143666, 2023). "M2 macrophages promote tumor angiogenesis in hypoxic areas by coordinating IL-1, TNF-α, and VEGF." (PMID 37107298, 2023). "Additionally, tumor cell pyroptosis induced by chemotherapeutic drugs or macrophage-derived tumor necrosis factor α (TNF-α) can occur through the caspase-8/GSDMD/GSDME/GSDMC pathway." (PMID 38264354, 2023). "We recently reported that Poly6 could elicit a strong anticancer immune response via the production of TNF/iNOS-producing dendritic cells (Tip-DCs) in an IFN-I-dependent manner in a tumor-bearing mouse model." (PMID 37334373, 2023). "Restimulation of peripheral blood mononuclear cells (PBMCs) from AU-011 PDT treated animals with irradiated TC-1 cells ex vivo showed enhanced secretion of IFN-y with IL-2 and TNF-a with IL-2 compared to the relevant controls, indicating the existence of activated tumor specific lymphocytes." (PMID 36997666, 2023). "Additionally, flow cytometry revealed substantially higher levels of dendritic cells (DCs) and CD8+ T cells in draining lymph nodes and tumor tissue, as induced by pro-inflammatory molecules like IL-12 and TNF-α." (PMID 37139047, 2023). "Moreover, tumors from Usp5 cKO mice treated with Trametinib displayed reduced PD-1 expression and elevated IFN-γ, TNFα, and GzmB in tumor-infiltrating CD8+ T cells." (PMID 37208329, 2023). "For functions with NES less than zero, TNF (Tumour Tecrosis Factor) was the most frequent." (PMID 36945884, 2023). "Moreover, the frequencies of CD4+ and CD8+ T cells were significantly up-regulated in the tumor tissues, with substantial increases in IFNγ, TNFα and IL-17A expression in CD8+ T cells and augmented IL-17A expression in CD4+ T cells." (PMID 38074634, 2023). "A two-way circuitry is built in the HGOS microenvironment, because tumor cells secrete trophic factors for MDSCs as IL-1, IL-6, IL-10, TNF-α (tumor necrosis factor-α) and MCP-1 (monocyte chemoattractant protein 1), receiving as a cashback an immune niche favorable to their growth." (PMID 36614241, 2023).
tumor (continued). "However, chronic exposure to TNF-α in a detrimental inflammatory context has pro-tumor functions, including angiogenesis, metastasis, T cell apoptosis, and exhaustion." (PMID 37251409, 2023). "The results revealed that PI3K/AKT, TNF, and IL-17 signaling pathways play a key role in tumor proliferation and that PD may affect the activation of these pathways to inhibit the proliferation of HCC cells." (PMID 37950195, 2023). "Some studies have shown that IFN-γ collaborates with Toll-like receptor ligands to stimulate anti-tumor activity in pretreatment macrophages, increase nitric oxide (NO) production, and promote the production of pro-inflammatory molecules, such as TNF and IL-12 family cytokines." (PMID 36672865, 2023). "Even with the low levels of IL-12 released by activated T cells, we observed along with the increased production of pro-inflammatory cytokines, such as IFN-γ and TNF, the enhanced expression of GzmB, which is a major effector molecule of T cells for inducing apoptosis in tumor cells." (PMID 36793716, 2023). "In contrast, M1 macrophages are known to directly limit tumor growth through production of reactive oxygen species or by coordinating the anti-tumor immune response via secretion of inflammatory cytokines (e.g., TNF-α and IFN-γ)." (PMID 37936688, 2023). "In this regard, TNF-α may contribute to tumor progression by acting together with TGF-β to induce endothelial-to-mesenchymal transition." (PMID 38136358, 2023). "Tumor necrosis factor-α (TNF-α) is a cytokine co-secreted by TAMs and tumor cells." (PMID 37542283, 2023). "Furthermore, tumor-infiltrated γδT17 cells secrete IL-17, IL-8, TNF, and GM-CSF, which promote the proliferation of PMN-MDSC, forming an immunosuppressive microenvironment, thereby promoting tumor growth." (PMID 37597083, 2023). "Meanwhile, in our previous results, A3 could promote M1 polarization of macrophages in tumor tissues and increase the expression of the pro-inflammatory mediators TNF- α, IL-12, IL-6, and IL-1β." (PMID 36838599, 2023). "Similarly, protein levels of PCNA, cyclin D1, cyclin E, and MMP-9 decreased, whereas TNFα expression increased in the tumor area of the HCT-116 xenograft in nude mice." (PMID 36979011, 2023). "In the process of non-small cell bone metastasis, the activity of tumor secretory factors (such as IL-1, IL-6 and TNF-α) leads to excessive formation of osteoclasts, induces mobilization of bone marrow-derived cells that promote angiogenesis and tumor homing, and finally promotes tumor growth." (PMID 37652923, 2023). "Interestingly, NASH and most IMIDs share some molecular characteristics such the activation of the tumor pathways depending on tumor necrosis factor (TNF)-α or the imbalance in T-cell subtypes such as Th17/Treg." (PMID 37445895, 2023). "MerTK CAR M reduces tumor burden, increases median survival time, and creates an inflammatory environment by increasing the levels of proinflammatory cytokines in serum, such as IL-β, IL-6, TNF-α, and monocyte chemotactic protein (MCP)-1 In-vivo." (PMID 38017494, 2023). "For instance, TNF-α has been reported to promote tumor development and metastasis." (PMID 37124061, 2023). "It is known that KPF modulates the expression and activation of IL-1β and TNF-α and the NF-kB pathway is activated by TNF-α to promote tumor cell proliferation and the inhibition of apoptosis, and that it enhances the tumor angiogenesis ability and the potential of invasion and metastasis." (PMID 37445894, 2023). "However, the enhanced intratumoral accumulation of Foxp3UP CD8 T cells counteracted the negative effect of FoxP3 overexpression on cytokine production and resulted in a higher number of IFNγ+ TNFα+ CD8 T cells within the tumor." (PMID 36045586, 2023). "Anti-tumor effects mediated by antibody-based TNF-α delivery could also be increased by a proper combination with other cytokines, e.g., IL-2." (PMID 36839658, 2023).
tumor (continued). "Similar results were obtained in vivo where the elevated expression of IL-6 (approximately twofold), IL-1β (threefold), and TNF-(sixfold) was observed (the expression of the stated inflammatory markers was evaluated in XM-S and XM-R mouse models after 21 days of tumor induction)." (PMID 36840009, 2023). "Consistent with observed higher tumor growth rate, unmodified neutrophils gradually released more IL-6 and TNFα, which may lead to cytokine release syndrome in patients and require more in-depth safety studies with IL-6 blockers." (PMID 37080958, 2023). "The results above suggest that GPX4 knockdown may activate T-cell activity, leading to enhanced TIL infiltration and the type II TNF response to kill tumor cells." (PMID 37649598, 2023). "Interestingly, the inhibition of USP14 was showed to upregulate TNF-α expression in tumor cells and sensitize them to TNF-α and radiation-induced cytotoxicity." (PMID 37658402, 2023). "KEGG terms showed that the DEGs were enriched in biological pathways of the tumor initiation, progression, and stemness, including TNF signaling pathway, TGF-beta signaling pathway, and signaling pathways regulating pluripotency of stem cells and actin cytoskeleton." (PMID 37415224, 2023). "In addition, a variety of cytokines, including TNF-alpha (TNF-α), TGF-beta (TGF-β), MMP2 (matrix metalloproteinase-2), and MMP3, are associated with the proliferation, invasion and metastasis of tumor cells." (PMID 37895145, 2023). "Furthermore, radiation-mediated macrophage activation can induce radioresistance in cancer cells and enable tumor recurrence after radiotherapy by upregulating tumor necrosis factor-α (TNF-α) and angiogenesis." (PMID 38020914, 2023). "The family was also correlated with TNF-mediated anti-tumor responses." (PMID 37375003, 2023). "The results of these studies have demonstrated possible anti-tumor effects of anti-TNFα mAb." (PMID 36996146, 2023). "Infliximab may inhibit tumor cell proliferation by neutralizing TNF-α or inducing TNF-α-dependent apoptosis by depriving cells of the cytokine." (PMID 37711747, 2023). "In addition, macrophages can contribute to tumor-promoting inflammation through the secretion of immunostimulatory cytokines, such as interleukin-6 (IL-6), and tumor necrosis factor-alpha (TNFα)." (PMID 37509382, 2023). "Interestingly, NK cells in the tumor produced high levels of IFNγ but low levels of TNF compared to ILC1s, which correlated with antitumor activity of NK cells." (PMID 36969171, 2023). "Tumor-associated macrophages (TAMs), by secreting many factors, such as TGF-B, TNF-a, IL-1B, and IL-6, may be responsible for inducing the EMT process in CRC." (PMID 37185706, 2023). "Th2 cells always give rise to a humoral immune response that promotes tumor growth through the secretion of IL-10, IL-4, and TGF-β; by contrast, Th1 cells can secrete IFN-γ, TNF-α, and IL-12 to mediate the anti-tumor response and provide successful protection against cancer." (PMID 37345110, 2023). "ANGPTL8 may be induced by STAT3 signalling, FFAs or other proinflammatory cytokines, such as TNF-α and TGFβ1, in the tumour microenvironment, and it may affect the differentiation and development of tumours through the following pathways." (PMID 38107478, 2023). "Prior studies have indicated that TNFα, IL-1β, IL-6 promote tumor growth in obese mouse models." (PMID 37954072, 2023). "Also, IL-1, IL-6, and TNF-α were evaluated as they are considered key mediator cytokines of the inflammatory milieu and modulate tumor-promoting factors." (PMID 37068081, 2023). "However, numerous relationships within TNF-α signaling and differences depending on the stage and type of tumor hinder the development of precise diagnostics and treatment." (PMID 37233761, 2023). "TNF-α is mediated through nearly all of the TNF-α receptors on tumor cells and many other cells." (PMID 37994159, 2023).
tumor (continued). "In this regard, targeting of TNFα to tumor neo-vasculature by conjugation with a CNGRC peptide that binds the CD13 aminopeptidase N revealed a strong anti-tumor efficacy in several preclinical models, and it is being evaluated in clinical trials in melanoma and other solid tumors." (PMID 37376140, 2023). "The potential explanations for the contradictory effects of TNF on MDSCs may be that TNF is likely to exert differential effects on MDSCs depending on different stages and phenotypes of tumor development." (PMID 37206639, 2023). "Moreover, EVs can transfer pro-inflammatory factors, such as IL-6 and TNF-α, promoting an inflammatory milieu that supports tumor growth." (PMID 38052753, 2023). "Additionally, it also controls the inflammatory response within the tumor microenvironment by reducing the expression levels of TNF-α, IL-1β, and IL-6." (PMID 37894468, 2023). "Importantly, this map shows the transition of keywords from older “interleukin 2”, “BCG”, and “TNFα” to the newer “pdl-1”, “tumor microenvironment”, and “immune checkpoint inhibitor”." (PMID 37350946, 2023). "Moreover, IL-6 and TNF are also known to be tumor-promoting cytokines, with important roles in tumor initiation and progression." (PMID 38068717, 2023). "In addition, adipocytes co-cultured with breast cancer cells can promote the invasion of tumor cells by overexpressing the inflammatory cytokines such as IL-6, TNFα, and MMPs." (PMID 37666813, 2023). "A reduction-responsive RNAi nanoplatform has been developed to silence both MGLL and CB2 to inhibit the production of FFAs, which promotes the classical activation of TAMs to secrete tumor-killing cytokines, such as TNF-α and IL-12, to exert an inhibitory effect on pancreatic cancer." (PMID 37004014, 2023). "Indeed, adoptively transferred Tc17 cells gave rise to an increased number of IFN-γ/TNF-α co-producers, which correlates well with tumor rejection." (PMID 37205114, 2023). "CTLs could cooperate with cytokines such as interferon-γ(IFN-γ) and tumor necrosis factor-α (TNF-α) to reverse the immunosuppressive tumor microenvironment into an immunogenic phenotype, increasing immunotherapy responses of tumor cells." (PMID 36860309, 2023). "However, abnormal or excessive TNF-α activation can lead to or aggravate chronic inflammation and neoplastic diseases." (PMID 37554306, 2023). "Additionally, their tumor‐infiltrating lymphocytes exhibited impaired tumor necrosis factor‐alpha (TNF‐α) and interferon‐gamma (IFN‐γ) production, with an elevated programmed cell death protein 1 (PD‐1) level." (PMID 37691307, 2023). "First, we assessed the tumor homing of the RGD4C.TPA.TNFα particles upon systemic delivery." (PMID 37331004, 2023). "Moreover, TNF is an important effector molecule targeting immunogenic tumor cells during tumor surveillance, which is critically required for effective priming, proliferation and recruitment of tumor-specific T cells." (PMID 37047287, 2023). "In addition, the butyrate induces strong production of effector molecules in cytolytic T lymphocytes (CTLs) such as CD25, IFN-γ, and TNF-α, resulting in increased anti-tumor reactivity and improved therapeutic outcomes." (PMID 37108477, 2023). "However, as its name suggests, TNF-α should downregulate the proliferation of tumor cells and kill them." (PMID 37398678, 2023). "Second, IL-1α released by the tumor cells acts distally to induce TNFα expression in HSPCs." (PMID 37134077, 2023). "The effect of TNF-α on a tumor is determined by the dose and time." (PMID 37298230, 2023). "All three types of interferon increase the expression of cell surface antigens, such as tumor necrosis factor (TNF) receptors and MHC antigens, making tumor cells easier for cytotoxic leukocytes or TNF, a cytokine with cytostatic solid and cytotoxic effects, to recognize." (PMID 36874133, 2023).